ILK (integrin linked kinase)
Diseases named in the same sentence as ILK in open-access papers (continued):
Sharing a sentence is not in itself a finding about the gene and the disease.
ischemia (2 papers, 2015 to 2020). A hypoperfusion of the BLOOD through an organ or tissue caused by a PATHOLOGIC CONSTRICTION or obstruction of its BLOOD VESSELS, or an absence of BLOOD CIRCULATION. "Tβ4 promotes the survival of cardiac myocytes after ischemia, an effect that is mediated by the increased expression of vascular endothelial growth factor (VEGF) and activation of integrin-linked kinase (ILK)." (PMID 26006229, 2015). "On the other hand, in the ischemia region of the bladder tissue, the ILK gene-modified BMSC treatment significantly increased the number of the blood vessels, which could improve the harsh ischemia microenvironment." (PMID 32650831, 2020). "In this study, we aimed to investigate whether the treatment of DCP with ILK gene-modified BMSCs enhanced stem cell engraftment, induced vascular formation, relieved ischemia in the transplanted region, and promoted bladder function recovery." (PMID 32650831, 2020).
keloid (2 papers, 2022 to 2023). An irregularly shaped, elevated mark on the skin caused by deposits of excessive amounts of collagen during wound healing. "The aim of this study was to investigate the expression of key Hippo pathway molecules and ILK in hypertrophic scars and keloids." (PMID 36359821, 2022). "We also showed that ILK is overexpressed in fibroblasts of keloids and hypertrophic scars with significantly higher expression in keloids compared to hypertrophic scars and control skin, providing evidence that implicates ILK in skin scarring." (PMID 36359821, 2022). "In this study, we provide novel evidence implicating Hippo pathway deregulation and ILK overexpression in the formation of keloids and hypertrophic scars." (PMID 36359821, 2022). "Overall, future studies elucidating the role of the Hippo pathway and ILK in skin wound healing and scarring may lead to the development of novel therapeutic options for keloids." (PMID 36359821, 2022). "In conclusion, our study showed that nuclear YAP, TAZ and TEAD expression, a-SMA positive myofibroblasts and ILK expression are significantly higher in keloids compared with hypertrophic scar tissue and control skin, suggesting their involvement in the pathophysiology of skin scarring." (PMID 36359821, 2022). "Moreover, a significant positive correlation between the activation of YAP, TAZ and TEAD and the overexpression of ILK has been evidenced in keloids and hypertrophic scars, suggesting an interplay between Hippo and ILK pathways in the process of aberrant wound healing." (PMID 36359821, 2022).
laryngeal carcinoma (2 papers, 2011 to 2018). Carcinoma that arises from the laryngeal epithelium. "Recently we found that integrin-linked kinase (ILK) and p-Akt are overexpressed in laryngeal carcinoma." (PMID 22191056, 2011). "In further support to the implication of parvins and PINCH1 in human laryngeal cancer, we have previously shown that ILK, their binding partner, is overexpressed in laryngeal cancer." (PMID 29755929, 2018). "A reverse correlation between nuclear AR and cytoplasmic ILK expression was evidenced, indicating an interaction of those molecules in laryngeal carcinoma." (PMID 22191056, 2011). "It seems that ILK could oppose the activation of ARs in laryngeal carcinoma and thus their tumor proliferative function." (PMID 22191056, 2011). "Additionally, in the current study we show a correlation of low expression of AR in tumors with ILK cytoplasmic overexpression (r = −0.260, P = 0.01) which possibly suggests an interaction of those molecules in laryngeal cancer, yet not in line with the hypothesis of ARs being activated by ILK." (PMID 22191056, 2011).
metastatic cancer (2 papers, 2022). A carcinoma which has spread from the original site of growth to another anatomic site. "The ILK/LIMD2 complex and the regulation of ILK activity by LIMD2 suggest a potential mechanism for upregulation of ILK activity specifically in metastatic cancer cells." (PMID 35804980, 2022). "Interestingly, it has been shown that Parvin and ILK control the formation of filopodia by blocking the cofilin-mediated F-actin severing in metastatic cancer cells." (PMID 36531940, 2022).
Peritoneal Fibrosis (2 papers, 2023 to 2025). Disorder characterized by a wide range of structural changes in PERITONEUM, resulting from fibrogenic or inflammatory processes. "Since peritoneal fibrosis induced by long‐term PD can lead to functional injury in the peritoneum, we then evaluated the level of ILK in PD effluent‐derived EVs and found a positive linear association between percentage of ILK+ EVs and 4 h D/P Cre." (PMID 37357686, 2023). "In summary, our data indicate that ILK‐enriched EVs derived from injured mesothelial cells activate resident fibroblasts to promote peritoneal fibrosis." (PMID 37357686, 2023). "ILK+ EVs can be used as a biomarker for peritoneal function and potential therapeutic target to treat peritoneal fibrosis." (PMID 37357686, 2023). "Notably, we confirmed that ILK is up‐regulated in human fibrotic peritoneum compared to normal peritoneum, supporting the notion that ILK regulates peritoneal fibrosis, as noted in cell cultures and mice." (PMID 37357686, 2023). "Targeting EVs or ILK could provide a novel therapeutic strategy to combat peritoneal fibrosis." (PMID 37357686, 2023). "We next sought to determine whether knockdown of ILK can alleviate mouse peritoneal fibrosis." (PMID 37357686, 2023). "Thus, targeting ILK is a potential therapeutic strategy to prevent PD‐induced peritoneal fibrosis." (PMID 37357686, 2023).
renal agenesis (2 papers, 2014). Renal agenesis (RA) is a form of renal tract malformation characterized by the complete absence of development of one or both kidneys (unilateral RA or bilateral RA respectively), accompanied by absent ureter(s). "Mutations in ILK K220 disrupt α-parvin binding and cause renal agenesis." (PMID 25352829, 2014). "Mice, which express ILK, that cannot bind to α-parvin display renal agenesis." (PMID 25352829, 2014). "In ILK, the KtoA mutation led to renal agenesis during kidney development, even though ILK has no catalytic activity." (PMID 24850911, 2014).
Salmonella Infections (2 papers, 2020 to 2026). Infections with bacteria of the genus SALMONELLA. "Mechanistically, the EcN outer membrane protein MipA was identified as a key factor that induces the upregulation of integrin-linked kinase (ILK), thereby reinforcing tight junction integrity and restricting Salmonella infection." (PMID 41823703, 2026).
serous ovarian tumors (2 papers, 2024). "Moreover, TCGA datasets confirmed that combined expression of ILK and Fzd7 in high grade serous ovarian tumors is correlated with reduced response to chemotherapy and poor patient outcomes." (PMID 38559125, 2024).
skin infection (2 papers, 2024). An inflammatory process affecting the skin, caused by bacteria, viruses, parasites, or fungi. "In contrast, one study found that in mouse skin lacking integrin-linked kinase in the epidermis, S. aureus penetrated the skin 35 times more than normal skin; thus, integrin-linked kinase has potential as a targeted therapy for the prevention of S. aureus skin infections." (PMID 38505290, 2024). "In contrast, a study reported that in mice, S. aureus penetrated skin lacking ILK in the epidermis 35 times more than normal skin, indicating the great potential of ILK as a targeted therapy for the prevention of S. aureus skin infections." (PMID 39015251, 2024).
skin tumor (2 papers, 2021 to 2022). "A previous study showed that PPARβ/δ promotes HRAS-induced senescence and skin tumor suppression by repressing p-AKT signalling via ILK repression." (PMID 35778385, 2022). "For example, cellular senescence markers like SA-β-gal are induced in skin tumors and benign colon adenomas by peroxisome proliferator-activated receptor-β/δ (PPARβ/δ) via repressing ILK and pAkt." (PMID 34163519, 2021). "One study has shown that cellular senescence is induced and suppressed skin tumors and benign colon adenomas by peroxisome proliferator-activated receptor-β/δ (PPARβ/δ) via repressing ILK expression and Akt phosphorylation (pAkt)." (PMID 34163519, 2021).
triple-negative breast carcinoma (2 papers, 2016 to 2023). An invasive breast carcinoma which is negative for expression of estrogen receptor (ER), progesterone receptor (PR), and human epidermal growth factor receptor 2 (HER2). "For example, an unbiased genome-wide CRISPR-Cas 9 screen in triple-negative breast cancer revealed that loss of ILK and its binding partners α-parvin and PINCH-1 potentiated the inhibitory effect of bosutinib, a SRC/ABL kinase inhibitor." (PMID 37508338, 2023).
age (1 paper, 2015). A temporal measurement of the time period elapsed since an identifiable point in the life cycle of an organism. "Further experiments will be necessary to analyze the potential therapeutic implications of the inhibition of ILK in age-related renal pathologies." (PMID 26583057, 2015).
anaplastic thyroid cancer (1 paper, 2021). "Integrin linked kinase has also been studied, showing an elevated expression in anaplastic thyroid cancer." (PMID 34063063, 2021).
aneurysm (1 paper, 2013). Bulging or ballooning in an area of an artery secondary to arterial wall weakening. "Our findings resemble those seen in Pinch1 and β1 integrin conditional mutant mice, and therefore support that, in neural crest-derived cells, ILK and Pinch1 act as cytoplasmic effectors of β1 integrin in a pathway that protects against aneurysms." (PMID 23744273, 2013). "This phenotype closely resembles that seen in Pinch1, Rac1 and β1 integrin conditional mutant mice; therefore, our results support that, in neural-crest-derived cells, ILK and Pinch1 act as cytoplasmic effectors of β1 integrin in a pathway that protects against aneurysms." (PMID 23744273, 2013). "Based upon published results and our own, we propose that β1 integrin, ILK, Pinch1, Rac1 and Smad3 participate in a common pathway involved in an NCC morphogenetic program during cardiovascular development that, when perturbed, results in aneurysms in the ascending aorta." (PMID 23744273, 2013).
aphakia (1 paper, 2007). "The aphakia seen in congenital cataracts may share similar mechanisms to those contributing to the aphakia in our β1 and ILK mutants." (PMID 19936087, 2007).
Arterial thrombosis (1 paper, 2021). The formation of a blood clot inside an artery. "ILK levels are increased in arterial thrombosis patients, and ILK-/- mice showed reduced platelet activation and subsequent aggregation, leading to unstable thrombosis." (PMID 34381164, 2021).
autoimmune disease (1 paper, 2018). A disorder resulting from loss of function or tissue destruction of an organ or multiple organs, arising from humoral or cellular immune responses of the individual to their own tissue constituents. "Our finding of the enhanced enrichment of ILK in ERU cases indicates a deviant influence of DOCK8 on inter- and intracellular signaling in autoimmune disease." (PMID 30120291, 2018).
Autoimmunity (1 paper, 2018). The occurrence of an immune reaction against the organism's own cells or tissues. "Since the role of ILK in autoimmunity is yet to be unraveled, we further characterized the role of ILK in PBL of controls and autoimmune cases." (PMID 30120291, 2018).
bladder tumor (1 paper, 2014). "Aside from the cell-type dependent action on the integrin receptors, amygdalin homogeneously diminished expression of ILK (minor) and activation of FAK (major) in all bladder tumor cell lines used in this investigation." (PMID 25333694, 2014).
brain cancer (1 paper, 2014). A primary or metastatic malignant neoplasm affecting the brain. "In other cancer cell lines (including breast, cervical, prostate or brain cancer cells), ILK loss resulted in mitotic arrest." (PMID 24911651, 2014).
Cachexia (1 paper, 2023). Severe weight loss, wasting of muscle, loss of appetite, and general debility related to a chronic disease. "Since myeloid-ILK deficiency improves body weight loss in APCmin/+ mice and cancer-associated cachexia is associated with a poor outcomes with a reduced survival rate, it was of interest to determine whether myeloid-ILK deficiency confers a protective effect and prolonged survival in APCmin/+ mice." (PMID 38077324, 2023).
calcific (1 paper, 2022). "ILK presented a significant association with valve calcification (adjusted OR, 0.0096; SD, 0.157; p < 0.005), with dyslipidemia being equally relevant (OR, 4.63; SD, 2.71; p < 0.009)." (PMID 36139812, 2022).
chondrodysplasia (1 paper, 2022). "During skeletal development, ILK-induced pathways are crucial for the proliferation and differentiation of chondrocytes within the growth plate, while depletion of ILK in chondrocytes causes dwarfism and chondrodysplasia." (PMID 35089438, 2022).
chondrosarcoma (1 paper, 2020). A malignant cartilaginous matrix-producing mesenchymal neoplasm arising from the bone and soft tissue. "In addition, Et-1 was shown to increase the expression of VEGF and angiogenesis via ILK, resulting in the migration and tube formation of chondrosarcoma cells." (PMID 32873319, 2020).
cocaine abuse (1 paper, 2015). Disorders related or resulting from use of cocaine. "The present study has shown that long-term behavioral sensitization to cocaine is accompanied by increases in BDNF, TrkB, p75NTR, ILK, and phospho-Ser473 Akt protein levels in the mPFC and NAc core — two brain areas that have been demonstrated to be intimately involved in cocaine abuse." (PMID 26538265, 2015).
cognitive deficits (1 paper, 2015). "In the present study, we hypothesized that cognitive deficits accompanying moderate prenatal alcohol exposure is associated with impairments of the ILK pathway." (PMID 26305322, 2015). "Therefore, we hypothesize that the cognitive deficits accompanying FASD are associated with impairments in the ILK signaling pathway." (PMID 26305322, 2015). "Thus, the present results identify ILK as an important molecule, whose activity warrants further research in models of FASD-induced cognitive deficits." (PMID 26305322, 2015).
dengue (1 paper, 2023). "Also, it would be essential to examine if ILK expression is elevated in DENV-infected patients with comorbidities who are susceptible to develop severe dengue." (PMID 36930690, 2023).
endocrine cancer (1 paper, 2024). "Studies have found that integrin-linked kinase can activate AKT to lead to EMT, and down-regulating integrin-linked kinase can inhibit EMT and metastasis of tumor cells in endocrine cancer." (PMID 39403386, 2024).
Familial adenomatous polyposis (1 paper, 2003). Familial adenomatous polyposis (FAP) is characterized by the development of hundreds to thousands of adenomas in the rectum and colon during the second decade of life. "In addition to this, we demonstrated that ILK signalling is dysregulated in patients diagnosed with familial adenomatous polyposis (FAP)." (PMID 12771992, 2003).
gallbladder cancer (1 paper, 2022). "We demonstrated that integrin-linked kinase (ILK) is one such candidate target, and an ILK inhibitor suppressed the proliferation of patient-derived gallbladder cancer organoids." (PMID 35629212, 2022).
glomerular diseases (1 paper, 2020). "Periostin can activate integrin-linked kinase(ILK) and affect the survival, proliferation, differentiation and apoptosis of cells by binding to integrin α/β subunits, participating in the progression of glomerular diseases accompanied with proteinuria." (PMID 33241962, 2020).
graft versus host disease (1 paper, 2023). An immune system disorder that occurs after allogeneic hematopoietic stem cell transplant and is a reaction of donor immune cells against host tissues. "Belumosudil, the drug shown to have the highest affinity for ILK in drug docking, is an FDA-approved drug for use against graft-versus-host disease and is known to target the polymerization of G-actin fibrils and inhibit the Rho-ROCK-MRTF pathway." (PMID 37887327, 2023).
head and neck cancer (1 paper, 2018). A primary or metastatic malignant neoplasm affecting the head and neck. "In contrast, ILK inhibitor could attenuate growth of head and neck cancer cells." (PMID 30002625, 2018).
hepatitis C virus infection (1 paper, 2022). A viral infection caused by the hepatitis C virus. "ILK increases the hepatitis C virus infection by inhibiting IFN-α-induced PKR activation and ISG15 expression." (PMID 35350437, 2022). "ILK also increases hepatitis C virus infection by suppressing type I interferon (IFN) and IFN-stimulated gene (ISG) expression." (PMID 35350437, 2022).
Huntington disease (1 paper, 2020). Huntington disease (HD) is a rare neurodegenerative disorder of the central nervous system characterized by unwanted choreatic movements, behavioral and psychiatric disturbances and dementia. "By contrast, only 11 signal transduction genes, such as HIPPO, ILK, RhoGDI, eIF4, p70S6K, and Huntington’s disease, were upregulated in both the 6-h and 5-day-out treatments." (PMID 32678123, 2020).
Hypercholesterolemia (1 paper, 2023). An increased concentration of cholesterol in the blood. "The observed downregulation of integrins, integrin-related proteins (ITGB1 and ILK) and TGF-β in the presence of oxLDL may impair the normal adaptive response to exercise in individuals with hypercholesterolemia." (PMID 36927534, 2023).
Inguinal hernia (1 paper, 2023). Protrusion of the contents of the abdominal cavity through the inguinal canal. "To validate the increased level of ILK in LPD effluent‐derived EVs, we gathered a cohort of 64 samples that were collected from nine inguinal hernia patients with normal renal function and 55 patients undergoing PD." (PMID 37357686, 2023).
ischemic stroke (1 paper, 2023). A stroke disorder caused by obstruction of blood flow to the brain, due to thrombotic (local blood clot formation) or embolic (due to a blood clot or other material traveling from another site) event. "Furthermore, the result of IPA suggested targeting the inflammasome pathway, integrin-linked kinase signaling pathway, and Th1 signaling pathway for treating ischemic stroke." (PMID 37533068, 2023). "Hence, targeting the ILK and Th1 pathways might be a potentially efficacious clinical approach for treating ischemic stroke." (PMID 37533068, 2023).
laryngeal tumors (1 paper, 2018). "Different ILK expression levels or preferential formation of an IPP complex containing β-parvin instead of a-parvin in some tumors may for example account for the higher positivity ratio of β-parvin, observed in laryngeal tumors, compared to α-parvin." (PMID 29755929, 2018).
leukoplakia (1 paper, 2017). A white patch or plaque on a mucous membrane that cannot be characterized clinically or pathologically as any other disease. "Unlike in OSCC, the average levels of iPANDA values for AKT/mTOR and other survival and mitogenic pathways, such as ERK, JNK, RAS/MAPK, p38, PAK, integrin/ILK and TGFβ signaling, were substantially lower in most leukoplakia samples when compared to the normal cohort." (PMID 28580171, 2017). "Notably, several sub-branches of ILK, IGF1R, HIF1, HGF, MAPK and WNT pathways were among the most differentially dysregulated axes between OSCC and leukoplakia, suggesting their role in the transition from non-invasive to invasive disease." (PMID 28580171, 2017).
liver failure (1 paper, 2011). A liver disease characterized by the liver losing or has lost all of its function. "Together the data suggests that reduced expression of FAS receptor in the ILK KO mice along with persistent upregulation of survival signals like ERK1/2 and NFκB signaling is the mechanism behind protection of ILK KO mice against Jo-2 induced liver failure." (PMID 22104495, 2011).
lupus (1 paper, 2019). "Substantial increase in ILK protein level was observed in kidney of lupus-prone mice, compare with the normal ones, and DZ2002 administration significantly reversed the elevation of ILK." (PMID 30696480, 2019).